TRPM7 (transient receptor potential cation channel subfamily M member 7)
Diseases named in the same sentence as TRPM7 in open-access papers (continued):
Sharing a sentence is not in itself a finding about the gene and the disease.
tumor (continued). "Together, these experiments indicate that high TRPM7 expression levels promote tumor metastasis formation in vivo." (PMID 25797249, 2015). "A recent study linking TRPM7 to cell migration and tumor metastasis also suggests the potential of TRPM7 as a strong and independent prognostic marker of poor prognosis of metastatic breast cancer." (PMID 23594099, 2013). "Targeting Mg2+ transporters—such as CNNM2 inhibitors or TRPM7 activators—may simultaneously block tumor Mg2+ uptake and amplify T cell functionality." (PMID 41174507, 2025). "PRL binding inhibits CNNM-mediated magnesium export and enhances TRPM7-driven import, altering intracellular magnesium levels, although the direct contribution of these changes to tumor progression remains unclear." (PMID 40463094, 2025). "The inhibition of Ca2+ influx channels such as TRPM7 repressed the aggressive tumor phenotype." (PMID 38255793, 2024). "Data show that the TRPM7 chanzyme is expressed in most tumor cell types." (PMID 38255793, 2024). "Furthermore, TRPM7 was shown to be a negative regulator of the tumor suppressor microRNA (miR)-28-5p." (PMID 38255793, 2024). "The downregulation of TRPM7 reduced the invasiveness and motility of the tumor cells." (PMID 38255793, 2024). "The downregulation of TRPM7 prevented the migration and invasion of tumor cells." (PMID 38255793, 2024). "TRPM7 regulates tumor proliferation by continuously activating the JAK2/STAT3 signaling pathway." (PMID 39759147, 2024). "However, surprisingly, TRPM7 was suggested to reduce the cell proliferation, migration and invasion of tumor cells." (PMID 38255793, 2024). "TRPM7 can regulate tumor growth by modulating the AKT/FOXO1 axis." (PMID 35721115, 2022). "Furthermore, TRPM7 silencing significantly decreased the tumor sizes and weights in a mouse xenograft of SKOV3 tumors (P < 0.01)." (PMID 35101076, 2022). "Furthermore, it will be interesting to verify the expression of TRPM7 and the Mg content in different HCCs classified according to their molecular activation pathways involved in tumor formation/progression." (PMID 34312420, 2021). "High TRPM7 expression is closely related to aggressive tumor behaviour and advanced TNM stage." (PMID 34938330, 2021). "In addition, aggressive tumours require TRPM7 channel activity and interaction with cytoskeletal proteins." (PMID 33617107, 2021). "However, clinical studies with large populations are needed to investigate the effect of TRPM7 expression in tumor tissues on the prognosis of patients with GC." (PMID 34938330, 2021). "These in vivo results indicate that TRPM7 has a crucial role in tumor growth." (PMID 32907556, 2020). "TRPM7 inhibitors showed anti-proliferative effects on many cultured tumour-derived cells." (PMID 32977698, 2020). "Increasing evidence shows that TRPM7 plays a critical role in tumor cell proliferation and invasion, suggesting that TRPM7 could be a therapeutic target in human malignancies." (PMID 33381038, 2020). "Recently, more mechanisms by which TRPM7's contribution to tumor formation have been explored." (PMID 33381038, 2020). "The mechanisms by which TRPM7 facilitates the viability of tumor cells vary." (PMID 33381038, 2020). "Furthermore, TRPM7 silencing reduced the numbers and sizes of metastatic lung tumors at 30 days post inoculation and prolonged the survival of tumor-bearing mice (P < 0.05)." (PMID 30819230, 2019). "We identified TRPM7 as the molecular mechanism by which systemic Mg2+ homeostasis is regulated and developed a highly specific antagonist, waixenicin A, that suppresses growth of tumor cells in vitro." (PMID 28810912, 2017). "In addition, we also transplanted the T24 cells infected with lentiviral-TRPM7-shRNA (T24 LV-M7sh) to observe the tumor growth under downregulation of TRPM7 at transcriptional level." (PMID 27662662, 2016).
tumor (continued). "Importantly, we have established a T24-transplanted NOD/SCID mouse model with carvacrol and lentiviral-shRNA treatment respectively, observing a significant delayed tumor growth by both reduction of TRPM7 protein activity and TRPM7 gene transcription." (PMID 27662662, 2016). "Furthermore, a NOD/SCID mouse model transplanted using the BCa cells was established, revealing delayed tumor growth by reduced protein activity and mRNA transcription of TRPM7 in vivo." (PMID 27662662, 2016). "Furthermore, it was suggested that TRPM7 plays a role in anoxic neuronal death, hypertension, neurodegenerative disorders, atrial fibrillation, cardiac fibrosis and tumor growth/progression." (PMID 25437439, 2014). "Interestingly, TRPM7 mRNA expression was found in all tumor samples, and was significantly correlated with both MYCN amplification (p = 2.3 × 10−7) and mRNA expression (p = 3.5 × 10−3 in a 2logPearson test)." (PMID 25277194, 2014). "Downregulation of TRPM7 decreased the motility of fibroblasts and tumor cells." (PMID 22952790, 2012). "Moreover, TRPM7 expression positively correlated with tumor grade." (PMID 38255793, 2024). "TRPM7 regulates the levels of Ca2+, which can alter the signaling pathways involved in survival, cell cycle progression, proliferation, growth, migration, invasion, epithelial-mesenchymal transition and thus determines cell behavior, promoting tumor development." (PMID 34944940, 2021). "In addition, the TRPM7 inhibitor, carvacrol, limited the tumor size in a xenograft model." (PMID 32907556, 2020). "In addition, we evaluated whether the TRPM7 inhibitor, carvacrol, inhibited tumor size in a xenograft model." (PMID 32907556, 2020). "Moreover, we demonstrated that suppression of TRPM7 inhibits tumor growth in a xenograft model." (PMID 32907556, 2020). "By analyzing the GSE62254 dataset, we found a significant association of prognostic CaRG expression with tumor stages for TRPC1, CACNA1H, and TRPM7, while no genes resulted in being significantly associated with tumor stages from the analysis of the GSE15460 dataset." (PMID 31083561, 2019). "The importance of TRPM7 in cellular Mg2+ homeostasis has been investigated in several cell types, including leukocytes, platelets, vascular smooth muscle cells (VSMCs), cardiomyocytes, cardiac fibroblasts, osteoblasts, and tumor cells, in both physiological and pathological conditions." (PMID 30995736, 2019). "In addition, TRPM7 is also known for its role in tumor cell proliferation." (PMID 29772843, 2018). "Moreover, TRPM7 is required for proliferation and migration of several types of tumor cells." (PMID 28094304, 2017). "However, the mechanisms by which TRPM7 drives tumor progression remain poorly understood." (PMID 25797249, 2015). "Specifically, TRPM1 and TRPM2 were upregulated in tumor tissues, whereas TRPM4, TRPM6, TRPM7, and TRPM8 were downregulated in the tumor group." (PMID 41562086, 2025). "TRPM7 enhances the expression of angiogenesis factors, such as VEGFA, by activating specific pathways, thereby promoting tumor angiogenesis." (PMID 40740874, 2025). "Some recent studies have highlighted the crucial role of two types of TRP channels, TRPM7 and TRPM8, in regulating cell metabolism in certain tumor types." (PMID 40813985, 2025). "In this section, we discuss recent findings involving TRPM7 and TRPM8 in metabolic reprogramming in different tumor types." (PMID 40813985, 2025). "Thus, TRPM7 chanzyme may be a promising target in tumor therapy." (PMID 38255793, 2024). "TRPM7 and TRPM8 are highly expressed in human breast ductal adenocarcinoma (hBDA) compared to adjacent non-tumor cells, with their expression levels correlating to specific pathological parameters." (PMID 39633507, 2024). "We observed that TRPM7 and POSTN expression is significantly enriched in CAFs (p < 10−15) and to a lower extent in endothelial cells from PAAD tumor samples compared with a normal pancreas from GTEX." (PMID 35883700, 2022).
tumor (continued). "TRPM7 has been reported to regulate migration and invasion of KIRC tumor cells via phosphorylating Akt signaling pathways." (PMID 36588677, 2022). "TRPM7 expression and Factor XIIIa-expressing TAM density were immunohistochemically evaluated in paraffin-embedded tumor tissues of 204 GC patients undergoing surgery at a single institution." (PMID 34938330, 2021). "Among miR-28-5p targets, expression of Rap1b appeared as being positively correlated with TRPM7 in GBM and was up-regulated in tumor samples due to the suppression of the repressing role of miR-28-5p." (PMID 33928077, 2021). "TRPM7 and TRPM8 expression is importantly correlated with the Scarff-Bloom-Richardson (SBR) grade, Ki67 proliferation index, and tumor size." (PMID 29875336, 2018). "Previous studies have shown that FTY-720 inhibits NB tumor growth by inhibiting sphingosine kinase 2, and FTY-720 inhibits TRPM7 in HEK-293 cells stably expressing TRPM7." (PMID 29299124, 2017). "Despite these effects at cellular and molecular levels, we did not observe any effect of the TRPM7 kinase deletion on tumor growth nor on micrometastasis detection in mice xenografted with MIA PaCa-2 cells." (PMID 40274768, 2025). "Upregulated genes were primarily associated with cell adhesion/invasion/metastasis (ELMO2, ADAM9, DLG1, TRPM7), metabolism/mitochondrial function (FAM120A, DARS2), and cellular transport/axonal trafficking (KIF1B, TBC1D5), indicating the presence of tumor microenvironment stress." (PMID 41404060, 2025). "Stabilizes TRPM7 mRNA, increases VEGFA expression, promotes tumor angiogenesis." (PMID 40740874, 2025). "This suggests that TRPM7 kinase deletion has no impact on KRAS G12C tumor progression nor metastasis dissemination." (PMID 40274768, 2025). "In many studies, TRPM7 expression levels in tumor cells were not compared to thoser of normal cells." (PMID 38255793, 2024). "The release of OH− increases the extracellular pH of tumor cells, which is not conducive to the growth of tumor cells, Mg activates over 300 enzymes via interaction with the TRPM7 plasma channel α-kinase." (PMID 39223145, 2024). "Tumor vessel normalization, achieved through targeting glycolytic enzymes like PFKFB3 176, PKM2 177, TRPM7 178 and PDK 179 emerges as a promising anticancer strategy by improving vessel maturity and perfusion, thereby reducing tumor aggressiveness and enhancing chemotherapy effectiveness." (PMID 39479443, 2024). "Additionally, the intrinsic serine/threonine kinase activity of TRPM7 is crucial for EMT, cell migration, and the development of tumor metastasis." (PMID 39027429, 2024). "Using tumor samples derived from the tumor xenograft mouse models, we demonstrated that the expression of TRPM7, NFATC3, and ki67 proteins was significantly suppressed in the TRPM7-silenced and combined treatment mice compared with that in the control mice." (PMID 35771152, 2022). "As a result of all these findings, hypothetically, we thought that this positive correlation between TRPM7 expression and Factor XIIIa+ TAM density may be responsible for aggressive tumor behaviour and poor prognosis in GC patients with high TRPM7 expression." (PMID 34938330, 2021). "In addition, TRPM7 silencing decreased the lung metastasis of SKOV3 tumors and prolonged the survival of tumor-bearing mice." (PMID 30819230, 2019). "Unlike TRPM1 that plays the role of a tumor suppressor gene in melanoma, TRPM7 and TRPM8 are aberrantly expressed in pancreatic, gastric, breast and human head and neck cancers." (PMID 30477473, 2018). "Finally, the tumor growth and the detection of micrometastasis were not affected by the TRPM7 kinase deletion in mice xenografted with MIA PaCa-2 cells." (PMID 40274768, 2025). "Moreover, we noticed the upregulation of TRPM7 may be correlated with the EMT markers in the BCa tissue, which could reveal the malignancy of tumor." (PMID 27662662, 2016).
tumor (continued). "In addition, our studies have suggested that TRPM7 affects kidney injury, revealing a correlation between the TRPM family and cell ability, cell growth as well as Epithelial-Mesenchymal Transition (EMT), which was involved in malignancy of tumor." (PMID 27662662, 2016). "Transient receptor potential melastatin 7 (TRPM7) and vanilloid 2 (TRPV2) are nonselective cation channels that have become attractive target proteins for tumor studies due to their wide range of physiological and pathological functions 21-23." (PMID 35919815, 2022).
cardiovascular disease (11 papers, 2016 to 2023). "It has been suggested that TRPM7-mediated Ca2+ signalling could play a pivotal role in the development of fibrosis associated with cardiovascular disease and that TRPM7 could be an effective therapeutic target." (PMID 30523498, 2019). "Pharmacological regulation of TRPM7 can benefit patients with immune and cardiovascular disorders, tissue fibrosis and tumours and several small-molecule TRPM7 inhibitors and activators have been already examined preclinically." (PMID 37156763, 2023). "Selective pharmacological modulation of TRPM7 was proposed to be beneficial for patients with immune and cardiovascular disorders, tumors and other pathologies." (PMID 37156763, 2023). "This will open a door to develop LBQ657 as a new modulator to unravel TRPM7 channel vs. kinase function in cellular physiology and pathophysiology, and as a new therapy for various cardiovascular diseases." (PMID 34778271, 2021). "The adverse effects of TRPM7 in the development of cardiovascular disease is attributed to pathological Ca2+ influx through the TRPM7 ion channel and dysregulation of targets downstream of the TRPM7 kinase." (PMID 34682454, 2021). "Moreover, TRPM6 phosphorylates TRPM7 and can, therefore, modulate TRPM7 activity in cardiovascular diseases." (PMID 37764704, 2023). "In cardiovascular diseases, TRPM7 also has an anti-inflammatory effect." (PMID 36159330, 2022). "Our findings also suggest that a disease condition such as IHD could increase their expression, and this might indicate that TRPM7 as well as the TRPM6 are involved in the pathophysiology of cardiovascular diseases." (PMID 34326388, 2021). "Molecular mechanisms driving Mg2+-related cardiovascular disease are elusive, but altered TRPM7 function may be important." (PMID 31250885, 2020).
neurodegenerative disease (10 papers, 2014 to 2025). A disorder of the central nervous system characterized by gradual and progressive loss of neural tissue and neurologic function. "This has led to proposals that genetic variations in TRPM7 influence the susceptibility to neurodegenerative diseases." (PMID 33193064, 2020). "The TRPM7 variant T1482I was identified in some patients with neurodegenerative diseases that are associated with prolonged exposure to an environment deficient in Ca2+ and Mg2+." (PMID 25079291, 2014). "A recovery of the long‐term potentiation in the hippocampus was observed, where the treatment with CBGA and CBDA also restored the physiological expression level of TRPM7, a receptor channel involved in neurodegenerative diseases." (PMID 39510547, 2025). "Our results indicate that TRPM7 could be very useful as a molecular target for irreversible peripheral neurodegenerative diseases, facilitating discovery of new therapeutic methods for improving human health." (PMID 33029295, 2020). "Finally, the recent finding that CBDA and CBGA act as inhibitors of TRPM7, a receptor channel highly expressed in neuronal cells and supposed to play a relevant role in neurodegenerative diseases, prompted us to evaluate whether its expression level is affected by the treatment of βA peptide." (PMID 39510547, 2025).
kidney disease (4 papers, 2020 to 2024). "Changes in TRPM7 expression or activity can shape the fibrotic progression of kidney disease and pharmacologic interference with TRPM7 expression and/or function may offer therapeutic benefits to treat this debilitating condition." (PMID 32047249, 2020). "Moreover, it appears that the reno-protective effects of CBGA might be at least partially through reduced TRPM7 expression, but apparently targeting different cell types in the two kidney disease models." (PMID 37072467, 2023). "In the context of kidney disease, TRPM7 expression increases in UUO kidneys and systemic application of NS8593, a known TRPM7 inhibitor, prevents kidney atrophy in UUO kidneys, retains tubular formation, and reduces TRPM7 expression to normal levels." (PMID 37072467, 2023).
adenocarcinoma (3 papers, 2018 to 2024). A common cancer characterized by the presence of malignant glandular cells. "TRPM7, whose protein was found to be overexpressed in CRC and adenocarcinoma tissues, was instead unaltered at the mRNA level." (PMID 33923883, 2021).
heart disease (3 papers, 2012 to 2022). "A better understanding of the role of TRPM7 channels in their native environment will provide important clues on the mechanisms underlying various heart diseases." (PMID 22891975, 2012). "Nonetheless, the difference in patient age and heart disease would not affect the main outcome of the present study for demonstrating the evidence of TRPM7 channels in human atrial myocytes." (PMID 22802050, 2012).
neurological diseases (3 papers, 2018 to 2020). "Released Zn2+ contributes to the exacerbation of ischemic brain damage by gaining access to the intracellular space through proton-sensitive cation channels, such as TRPM7, indicating that zinc homeostasis can be disturbed by neurological disorders." (PMID 30486272, 2018). "It has been reported that inhibitors of TRPM7 are neuroprotective in various neurological diseases." (PMID 33114331, 2020). "Yet, little is known about a putative role of TRPM7 in neurological diseases." (PMID 30453391, 2019).
benign tumours (2 papers, 2012 to 2021). "Especially, in benign tumours, the correlation between histopathological diagnosis and pathological features was limited as it was difficult to obtain statistical data owing to the small number of benign tumours showing overexpression of TRPM7." (PMID 33617107, 2021). "The enhanced Ca2+ entry into the cell via TRPM7 channel could induce the intracellular Ca2+ overload (clinical Ca2+ paradox), which may lead to various heart pathologies." (PMID 22891975, 2012).
inflammation (2 papers, 2020 to 2023). Aberrant reaction of the microcirculation characterized by movement of fluid and leukocytes from the blood into extravascular tissues. "Consequently, authors concluded that the channel-kinase TRPM7 could have a protective role in cardiovascular inflammation and fibrosis." (PMID 33658993, 2020).
head and neck tumor (1 paper, 2013). "Based on the effects of midazolam, bradykinin and 2-APB, it may be concluded that pharmacological modulation of TRPM7 is a promising approach for preventing the growth and proliferation of human head and neck tumor cells." (PMID 23426784, 2013).
infection (1 paper, 2025). The state of being infected such as from the introduction of a foreign agent such as serum, vaccine, antigenic substance or organism. "The upregulation of TRPM7 highlights its role in cellular signaling and ion homeostasis, critical for the host’s response to infection." (PMID 41114509, 2025). "Additionally, genes involved in calcium signaling and ion channel regulation—PKD1, PKHD1, TRPC1, TRPM6, and TRPM7—highlight the importance of cellular homeostasis and signaling during infection." (PMID 41114509, 2025).
metabolic disorder (1 paper, 2023). "Considering the necessity of TAK1 polyubiquitination for TAK1 phosphorylation and IKK/NF-κB activation, we investigated whether TAK1 ubiquitination was involved in TRPM7-regulated adipocyte inflammation during metabolic disorders." (PMID 36717580, 2023).